AIF1L (allograft inflammatory factor 1 like)
Description:
Actin-binding protein that promotes actin bundling. May neither bind calcium nor depend on calcium for function.
Synonyms: C9orf58; IBA2; FLJ12783
Tractability: Antibody: UniProt places it where antibodies can reach, with high confidence; its Gene Ontology location is reachable by antibodies, with medium confidence. PROTAC: ubiquitination databases record sites on it.
Gene: Protein-coding gene on chromosome 9 (131,096,476 to 131,123,152, forward strand). Ensembl gene ENSG00000126878.
Subcellular location: Cytoplasm, cytoskeleton; Cell projection, ruffle membrane
Gene Ontology:
Molecular function: actin filament binding; calcium ion binding
Biological process: actin filament bundle assembly; ruffle assembly
Cellular component: actin cytoskeleton; actin filament; extracellular exosome; focal adhesion; ruffle membrane; cytoskeleton
Genetic constraint (gnomAD): Loss-of-function variants: 12 observed, 17.65 expected, observed/expected ratio (o/e) 0.68, 90% interval 0.44 to 1.1. The upper end of that interval is the gene's LOEUF score, 1.1, which puts it in group 4 of 6, group 1 being the genes least tolerant of losing a copy. Missense variants: 172 observed, 176.94 expected, observed/expected ratio (o/e) 0.97, 90% interval 0.86 to 1.1. Synonymous variants: 75 observed, 57.64 expected, observed/expected ratio (o/e) 1.3, 90% interval 1.08 to 1.58.
Homologues: Orthologues: chimpanzee AIF1L (100% identical), pig AIF1L (97% identical), mouse Aif1l (96% identical), rat Aif1l (96% identical), guinea pig AIF1L (95% identical), macaque AIF1L (85% identical), dog AIF1L (83% identical), zebrafish aif1l (76% identical), tropical clawed frog aif1l (63% identical). Paralogues in human: AIF1 (64% identical).
Diseases named in the same sentence as AIF1L in open-access papers:
AIF1L is named in the same sentence as 13 diseases in open-access papers, as found by Europe PMC text mining. Sharing a sentence is not in itself a finding about the gene and the disease. The quoted sentences say what the papers report.
breast carcinoma (5 papers, 2018 to 2025). "Al-though lower levels of AIF1L have been linked to poor prognosis during breast cancer, AIF1L overexpression in a cell line, similar to what is observed for our ME/CFS cohort, suppressed cell spreading and altered cell shape." (PMID 33572894, 2021). "PTGDS suppresses tumor growth via Wnt/β‐catenin modulation, while AIF1L plays a key role in regulating the cytoskeleton in breast cancer, contributing to cellular structure and function." (PMID 40784724, 2025). "More recently, increased expression levels for AIF1L were reported in cases of breast cancer and functionally related to increased proliferation rates via upregulation of cyclin D1." (PMID 30001384, 2018). "Only very recently, it was shown that AIF1L is highly expressed in conditions of breast cancer and correlates with proliferation behavior via modulation of cyclin-D1 levels." (PMID 30001384, 2018).
Obesity (3 papers, 2020 to 2026). Accumulation of substantial excess body fat. "AIF1L is associated with obesity and dynamically expressed during adipogenesis in goats." (PMID 41459085, 2025). "Because of the homology of these members of the AIF family and reported AIF1 associations with metabolism and obesity, we hypothesized that AIF1L might play a role in diet-induced obesity (DIO) and associated glucose insensitivity." (PMID 32107417, 2020). "This is the first study to investigate to report the functional role of AIF1L in the context of metabolism and obesity." (PMID 32107417, 2020). "Targeting AIF-1 or AIF1-like (AIF1L) may yield novel strategies to mitigate disease progression and enhance clinical management of obesity." (PMID 41694567, 2026). "Obesity-induced inflammation promotes the secretion of pro-inflammatory molecules and adipocyte degradation via macrophages, with allograft inflammatory factor 1-like (AIF1L) being involved in this process." (PMID 41459085, 2025). "We hypothesized that the characterization of a novel candidate protein, AIF1L, in a mouse model of obesity could help to discover novel regulatory proteins acting in key pathways." (PMID 32107417, 2020). "While studies in human populations suggest links between AIF1 and metabolic diseases such as obesity and diabetes, such associations with AIF1L have not been reported." (PMID 32107417, 2020). "Overall, despite these interesting effects on adipokine expression, these results combined suggest that AIF1L is not essential for the development of diet-induced obesity in male and female mice." (PMID 32107417, 2020). "In focused studies of AIF1L function in models of metabolic stress, including a HFD model of obesity, we found that loss of AIF1L did not affect maintenance of age-dependent body weight, HFD-induced weight gain, body composition, adipose depot size, or obesity-induced impairment of glucose handling." (PMID 32107417, 2020).
ovarian carcinoma (1 paper, 2014). A malignant neoplasm originating from the surface ovarian epithelium. "The other up-regulated genes in STOSE cells: Serpinb8, Epb41l4a, Aif1l, and Mgll have no known links to ovarian cancer." (PMID 24672774, 2014).
tumor (7 papers, 2015 to 2026). "For instance, mutations in the IGDCC4, ARHGEF18, MAP2K3 or AIF1L genes, which were observed in fractions exceeding 80% in the primary tumor ranged from 0 to 86% in the PDXs or secondary nodules." (PMID 26334103, 2015). "Knockdown of MYBL1 or overexpression of AIF1L exhibited synergistic anti-tumour effects when combined with PD-1 blockade." (PMID 41772383, 2026). "In human subjects with cancer, higher levels of AIF1L correspond to higher tumor grade and worse prognosis." (PMID 32107417, 2020). "Top differentially suppressed genes as the tumor transformed included SMOC1, BCAN, NES, AIF1L, ENC1, and IGF2 (p < 0.01)." (PMID 39256867, 2024). "It is also reported that knockdown of E2F1 inhibited tumor cell proliferation and promoted apoptosis in castration-resistant prostate cancer (CRPC) by regulating TMOD2 and AIF1L expression." (PMID 35392496, 2022).
cancer (3 papers, 2015 to 2020). A tumor composed of atypical neoplastic, often pleomorphic cells that invade other tissues. "Little is known about the role of AIF1L and KIAA0125 in pathogenesis of cancers." (PMID 26517675, 2015).
metabolic disease (1 paper, 2020). A congenital disorder (due to inherited enzyme abnormality) or acquired (due to failure of a metabolically important organ) disorder resulting from an abnormal metabolic process. "Drawing parallels based on structural similarity, we postulated that AIF1L might contribute to metabolic disorders, and studied it using mouse models." (PMID 32107417, 2020).
AIF1L also shares sentences with these, for which no sentence is quoted: atherosclerosis (2 papers); colon cancers (1); diabetes (1); endometriosis (1); ependymoma (1); infection (1); rheumatoid arthritis (1).